CXCL5 (C-X-C motif chemokine ligand 5)
Diseases named in the same sentence as CXCL5 in open-access papers (continued):
Sharing a sentence is not in itself a finding about the gene and the disease.
tumor (continued). "CXCL5 has been reported to participate in shaping tumor immune environment by inducing neutrophil migration through interaction with its receptor, CXCR231." (PMID 32201508, 2020). "Binding to its receptors, such as CXCR2, which is expressed in neutrophils, monocytes, eosinophils, endothelial cells and others, CXCL5 participates in immune cell recruitment, promotes angiogenesis and is involved in tumor progression." (PMID 32784743, 2020). "The culture supernatant from tumor tissues showed similar effects on neutrophils in a CXCL5-dependent manner." (PMID 32632106, 2020). "Neutrophil infiltration mediated by CXCL5 in laryngeal squamous cell carcinoma microenvironment leads to tumor cells escaping immune surveillance." (PMID 32632106, 2020). "They showed that the overexpression of CXCL5 was significantly correlated with poorer tumor differentiation and short patient survival." (PMID 32201508, 2020). "The culture supernatant from tumor tissues also enhanced the migration and invasion abilities of GC cells, however, this effect was reversed by pre-treatment with CXCL5 neutralizing antibody." (PMID 32632106, 2020). "CXCL5 can promote tumor progression in types of cancers by promoting proliferation and invasion of tumor cells." (PMID 32201508, 2020). "As predicated by bioinformatics, miR-588 directly targeted CXC chemokine ligand 5 (CXCL5), CXCL9, and CXCL10, which are associated with tumor-infiltrating immune cells in GC." (PMID 33323542, 2020). "The correlation between CXCL5 expression and clinicopathological features, prognosis and immune cell infiltration in tumor tissues was analyzed." (PMID 32201508, 2020). "High CXCL5 expression in tumor tissues was positively correlated with an advanced T stage (p=0.036), a positive tumor lymph node metastasis (p=0.014), a poor differentiation status (p=0.003) and a poor prognosis (p=0.001)." (PMID 32201508, 2020). "The recruitment of a variety of host-derived cells, that will eventually form the tumor stroma, is mediated by the chemokines CXCL5 and CXCL7, which are secreted by the platelets that become activated after interacting with the tumor cells." (PMID 32257952, 2020). "We report for the first time that endostatin, CXCL5, and proliferin are significantly secreted less by CTCs than primary tumor-derived cells." (PMID 31226820, 2019). "In this model, the authors were able to show that the CXCR2 ligands CXCL2 and CXCL5 are differentially expressed in tumor and stromal cells." (PMID 31561620, 2019). "Since CD163+ TAMs are activated by anti-PD1 antibody, the TAM-related chemokines such as sCD163 and CXCL5 are important to evaluate the recruitment of anti-PD1 antibody in the tumor microenvironment." (PMID 31080803, 2019). "Taken together, our findings support CXCL5 as an angiogenic factor that can promote cell metastasis through tumor angiogenesis in CRC." (PMID 30792394, 2019). "The combination of CXCL5 antibody, 1400 W or GM-CSF antibody with anti-PD-L1mAb resulted in increased number of T cells in primary tumour sites." (PMID 31819035, 2019). "The overexpression of CXCL5 by itself or plus the presence of intra-tumor neutrophils, is an independent prognostic indicator of overall survival and cumulative recurrence, as suggested by multivariate studies." (PMID 31799175, 2019). "Based on some molecular biological experiments in vitro and in vivo, we found that CXCL5 was upregulated in tumor tissues and that its level positively correlated with the expression of CD31." (PMID 30792394, 2019). "Patients expressing high levels of CXCL5 as well as high levels of elastase exhibited more advanced tumor stages." (PMID 30014484, 2019).
tumor (continued). "In A375 and M24met human melanoma, CXCL5 overexpression by tumor cells enhances neutrophil recruitment and infiltration into primary tumors and tumor lymphatic vessels." (PMID 31474975, 2019). "Testing these conditions has led to our discovery of a unique model system that can be used to investigate the role of additional chemokines like CXCL5 and their receptors in metastatic tumor colonization." (PMID 31562303, 2019). "Further, we report our observation of decreased MHCI expression and decreased secretion of endostatin, CXCL5, and proliferin by CTCs in comparison to primary tumor-derived cells." (PMID 31226820, 2019). "CXCL5/ENA-78 and IL-6 are cytokines that have been associated with tumour progression and have therefore the potential to cause serious side effects." (PMID 31010082, 2019). "HCC CTCs had significantly reduced major histocompatibility complex class I (MHCI) expression, as well as significantly decreased secretion of endostatin, CXCL5, and proliferin as compared to primary tumor-derived cells." (PMID 31226820, 2019). "rhCXCL5 can promote angiogenesis in vivo in Matrigel plugs, and the overexpression of CXCL5 can also increase microvessel density in vivo in a subcutaneous xenotransplanted tumor model in nude mice." (PMID 30792394, 2019). "In HCC patients, high levels of Axl and CXCL5 correlated with advanced tumor stages, recruitment of neutrophils into HCC tissue, and reduced survival." (PMID 30014484, 2019). "Staining of tumor tissues revealed that HLF‐T‐derived tumors express lower levels of CXCL5 compared with the exogenous overexpression in HLF tumors." (PMID 30014484, 2019). "Platelets are also involved in the recruitment of granulocytes to the tumor cell-platelet-agglomeration by secretion of chemokines CXCL5 and CXCL7, which activate the granulocyte expressed receptor CXCR2." (PMID 29346400, 2018). "The previous studies have shown that tumor cells produce oxysterol, C-X-C motif chemokine ligand 5 (CXCL5), hyaluronan fragments (HA), granulocyte-macrophage colony stimulating factor (GM-CSF), and macrophage migration inhibitory factor (MIF)." (PMID 30292233, 2018). "Recently, CXCL5 has been shown to be able to promote the proliferation, migration and invasion of various tumor cells and play pivotal roles in the pathogenesis and progression of cancer." (PMID 29743818, 2018). "Similar to the tumor cell-induced CXCL5 secretion, CXCL7 release was augmented in recalcified, fibrin free plasma in which thrombin formation was feasible." (PMID 29346400, 2018). "It is reported that the LC invasion and tumor growth can be inhibited by DACH1 through suppressing the CXCL5 signaling." (PMID 30364292, 2018). "Numerous cytokines, such as CXCL8, IL-6, and CXCL5, trigger inflammatory responses by recruiting and activating relevant inflammation cells in the tumor foci resulting in tumor growth, progression, and immunosuppression." (PMID 29636079, 2018). "ELISA analyses also revealed that the serum CXCL5 level was significantly higher in NPC patients than in the non-tumour patients (P < 0.001)." (PMID 29665837, 2018). "Because even in the same type of tumor, there are almost opposite conclusions about the prognostic value of CXCL5." (PMID 29743818, 2018). "It has been reported that IL-17a can induce CXCL5 production by liver tumor cells and enhance infiltration of MDSCs into tumor sites in a CXCL5/CXCR2 dependent manner." (PMID 29383101, 2017). "Most ELR+ CXC chemokines, including CXCL1–3 and CXCL5–8, increase the tumor tissue penetration of immunosuppressive cells, reduce apoptosis, and promote angiogenesis as well as tumor cell proliferation, migration, and invasion by activating the CXCR2 receptor." (PMID 29312644, 2017). "The upregulation of CXCL5 in tumor tissues was also positively correlated with a poor prognosis in CRC patients." (PMID 28356111, 2017). "Cxcl5 was expressed exclusively by tumor cells and Ppbp by tumor and host lung, myeloid, and liver cells." (PMID 28341702, 2017).
tumor (continued). "These and our findings suggest that the role of CXCL5 needs to be interpreted depending on the tumor context as this chemokine can lead to the infiltration of leukocytes that are able to mount an anti-tumor response." (PMID 28923105, 2017). "By binding to CXCR2, CXCL5 mediates various cellular behaviors including neutrophil trafficking, tumor cell migration and invasion." (PMID 28356111, 2017). "The analysis revealed that the high expression of CXCL5 was significantly correlated with tumor size (P = 0.047), Dukes’ stage (P = 0.003), tumor invasion (P = 0.009), lymph node localization (P = 0.002), and liver metastasis (P = 0.022)." (PMID 28356111, 2017). "It was thus exciting to discover that in addition to increased recruitment of VEGFR1+ BMDCs, there was upregulation of CXCL5 in the lungs of nude mice xenografted with Id1-expressing ESCC tumours." (PMID 28186102, 2017). "CXCL5 was significantly correlated with tumor size, Dukes’ stage, tumor invasion, lymph node localization, and liver metastasis." (PMID 28356111, 2017). "We next examined the expression of Cxcl5, Ppbp, and their cognate receptor genes, Cxcr1 and Cxcr2 in tumor cells and metastasis target organs of our models." (PMID 28341702, 2017). "The increased CXCL5 expression in RCC cells enhanced EC recruitment into the tumor microenvironment." (PMID 27848972, 2016). "Mechanistically, YAP upregulates the expression of C-X-C motif chemokine 5 (CXCL5) in tumor cells to recruit myeloid-derived suppressor cells, and appropriately, the use of antibodies to target CXCL5 suppresses tumor progression." (PMID 27589805, 2016). "Considering the multiple functions of CXCL5 in terms of proliferation, invasion, inflamation and tumor-environment interaction, our results further enrich the understanding of the underlying mechanism by which DACH1 acts as a tumor suppressor." (PMID 25788272, 2015). "Similar to GRO chemokines, ENA-78/CXCL5 chemo-attracts and activates neutrophils and has also been shown to possess tumor-promoting biological activities." (PMID 26361584, 2015). "The results showed that expression of CXCL5 was high in the cytoplasm of tumor cells expressing control vector, but very weak in tumor cells expressing DACH1." (PMID 25788272, 2015). "CXCL5 mRNA abundance was positively related to tumor size with lowest expression in T1 and highest in T3-4." (PMID 25788272, 2015). "From the hypoxically suppressed proinflammatory genes identified by RNA sequencing, four secreted inflammatory factors (CCL20, CXCL5, CSF2 and TNFα) associated with tumor inflammation were chosen for further validation." (PMID 25978030, 2015). "In deed, recent studies analyzed the effect of 18 out of the 23 differently expressed genes between the tumor and normal tissues on overall survival, only CXCL5 had significantly influence on overall and disease-free survival." (PMID 25788272, 2015). "The closely related CXCL5 protein, normally chemotactic for neutrophils, has also been shown to drive oral cancer cell growth and motility as well as enhance tumor angiogenesis." (PMID 25999952, 2015). "In hepatocellular carcinoma mouse model, it was reported that IL17, majorly produced by Vγ4+γδT cells, induced CXCL5 production by tumor cells, which enhance migration of MDSCs (myeloid-derived suppressor cells) expressing CXCR2 to the tumor site." (PMID 25699053, 2015). "Once activated, γδreg and γδ17 amplify the immunoregulatory process in different ways: IL-17 promotes VEGF production by cancer cells and macrophages, and CXCL5 production by tumor cells which, in turn, recruited MDSC." (PMID 25505472, 2014). "Higher expressions of CXCR1, CXCR2, and CXCR4 with their ligands CXCL5, CXCL8, and CXCL12 appear to be associated with tumor angiogenesis, metastasis, and poor survival in NSCLCs." (PMID 25271023, 2014). "We initially selected epithelial CXCL5 as the target from gene mapping result to investigate its chemo-attractive roles in the tumor cell recruitment." (PMID 25011526, 2014).
tumor (continued). "CXCL5 expression was directly correlated with tumor growth, tumor-derived angiogenesis, and metastatic potential." (PMID 24971349, 2014). "Chemotactic CXCL5 stimuli recruit C-X-C motif chemokine receptor (CXCR2)-positive myeloid-derived suppressor cells (MDSC) to the primary tumor." (PMID 24429391, 2014). "Upregulation of CXCL5 expression in tumor was found to be a favorable prognostic factor for both OS and DFS, and none of the analyzed clinicopathologic characteristics (patients’ age, gender, stage, or tumor histological type) influenced these associations." (PMID 24500664, 2014). "When NSCLC tumor-bearing animals were depleted of CXCL5, both tumor growth and spontaneous metastases were markedly attenuated." (PMID 24971349, 2014). "We found that mice with DNIIR expression had downregulated levels of CXCL1 and CXCL5 and as a result, fewer CD11b+Gr1+ cells in tumor tissue." (PMID 25280532, 2014). "There is evidence that tumor angiogenesis can be stimulated by tumor cell secreted CXC chemokine ligands CXCL5 and CXCL8, via their common receptor CXCR2." (PMID 23531764, 2013). "Supportive of the importance of NF-κB signaling in the pathogenesis of this tumor was our finding that 4 NF-κB target genes, IL-11, CXCL5, VEGFC, and CCL20, are on the list of strongly expressed genes from our gene expression profiling analysis." (PMID 24223206, 2013). "While no statistical differences in IL-1β, CCL-7, CCL-8, CCL-24 and CXCL-5 gene expression were confirmed among four tumor groups." (PMID 24260500, 2013). "The anti-angiogenic (CXCL9, CXCL10) and pro-angiogenic markers (VEGFa, CXCL2, CXCL5, Angiopoietin 1 and Angiopoietin 2) were quantified in the tumor by RTQPCR." (PMID 22815789, 2012). "Although methylation-specific PCR is not a quantitatively accurate method, the amount of PCR products indicated a higher degree of methylation of CXCL5 in all cell lines and two of the tumour samples compared to the normal osteoblasts." (PMID 23144859, 2012). "While it has been reported that CCL2, CXCL1 and CXCL5 are important for tumour growth, proliferation, and angiogenesis, the effect of these chemokines on DCs has not previously been documented." (PMID 22125641, 2011). "Recently, chemokines SDF-1 and CXCL5 have been shown to play a role in MDSC migration to tumor microenvironment." (PMID 20111717, 2010). "Dll4 is a key player in the Notch signalling pathway known to regulate tumour angiogenesis, as does Cxcl5, and growth." (PMID 19194513, 2009). "CXCL1 and CXCL5 mRNA expressions were significantly up-regulated in all CRC tissue specimens in relation to the matched tumor neighbor tissues (P < 0.001, respectively)." (PMID 18578857, 2008). "A recent review suggested recruitment of ASCs from ppWAT into PCa cells and the TME are precursors to tumor stromal cells and cancer‐associated fibroblasts and a source of IL‐6, TNFα, CXCL1, CXCL5, CXCL8, CXCL12, MCP‐1, and leptin facilitating tumor angiogenesis and cancer cell proliferation." (PMID 41450167, 2026). "It is worth mentioning that different CAF-derived factors such as CXCL2 and CXCL5 can also contribute to the expression of iICP receptors such as PD-L1 on tumor cells in a tumor-specific fashion, implying the involvement of a number of intracellular signaling mechanisms." (PMID 40805183, 2025). "Thus, SOX9 promotes the recruitment of immunosuppressive MDSCs through chemokine regulation—particularly via CXCL5—thereby inhibiting effector lymphocytes and facilitating tumor immune escape." (PMID 41293317, 2025). "Taken together, these findings suggest that CXCL5 may play a pivotal and complex role in tumor progression." (PMID 40313933, 2025). "Tumor promoter exposure in these mice leads to elevated levels of C-X-C motif chemokine ligand 5 (CXCL5) and macrophage colony-stimulating factor (M-CSF), promoting the accumulation of CD200R+ MDSCs and forkhead box P3 (FoxP3+) regulatory T cells while reducing activated CD4+ T cells in the skin." (PMID 40868818, 2025).
tumor (continued). "CXCR2 ligands such as CXCL1, CXCL2, CXCL3, and CXCL5 are highly expressed in the tumor microenvironment of KRAS-mutant preclinical models, although their elevated secretion is often attributed to stromal or immune cells rather than direct production by KRAS-mutant tumor cells." (PMID 40524071, 2025). "In addition, direct validation through in vitro or in vivo experiments is essential to establish the interaction between MRC1+ TAMs and CXCL5+SLC6A14+ tumor cells." (PMID 39670859, 2025). "Additionally, SOX2-driven upregulation of CXCL5 in NSCLC promotes the accumulation of tumor-associated neutrophils (TANs), accelerating tumor progression." (PMID 40303413, 2025). "Importantly, combined therapy using anti-CXCL5 and anti-PD-L1 antibodies synergistically suppresses tumor growth in vivo." (PMID 41254689, 2025). "The observed enrichment is consistent with evidence that platelets are rapidly recruited to disseminated tumor cells to form early metastatic niches via secretion of CXCL5/7, supporting the ability of DiRT normalization to detect platelet activation signatures associated with early tumorigenesis." (PMID 41300367, 2025). "Altogether, our results suggest that IFNγ is critical for promoting the growth and the expression of CXCL5 of 3D tumor cells and that TNFα may be a downstream effector molecule of LPS-stimulation." (PMID 40050422, 2025). "In NSCLC, CXCL5 plays a role in tumor growth, metastasis, and angiogenesis." (PMID 41149503, 2025). "CXCL5: This chemokine contributes to tumor metastasis and recurrence in various cancers." (PMID 41149503, 2025). "In addition to possibly playing a role in oncogenesis, tumor invasion, and metastasis in a range of pancreatic malignancies, CXCL5 can affect apoptosis in islet cells." (PMID 38884019, 2024). "CXCL5 was also correlated with neutrophils in peripheral blood in this study and may have promoted tumor development." (PMID 39235457, 2024). "We continued the research by seeking to determine whether CXCL5 knockdown affects tumor growth in xenograft studies." (PMID 39765818, 2024). "Furthermore, the detection of CXCL5 in tumor tissues from patients with NSCLC demonstrated that TAMs expressed higher levels of CXCL5 than other cells." (PMID 38642131, 2024). "Moreover, CXCL5 and IL-1β secreted by tumor cells correlated significantly to PMN-MDSCs accumulation, and antagonism against IL-1β or CXCR2 retarded tumor growth." (PMID 38649887, 2024). "The tumor-derived cytokines CXCL5 and CCL15 recruit immunosuppressive neutrophils and monocytes." (PMID 37142825, 2024). "CXCL5 also has a tumor-promoting effect and thus is crucial in tumor research and tumor immune microenvironment regulation, indicating that CXCL5 may be a key prognostic indicator for GBM." (PMID 38287266, 2024). "The results of tumor transcription spectroscopy showed that viral infection caused the increase of neutrophil chemokine 1(C-X-C ligand 1, CXCL1) and chemokine 5(C-X-C ligand 1, CXCL5), and induced neutrophil infiltration into infected tumor tissues." (PMID 39697335, 2024). "Additionally, we compared the differential expression of CXCL5 molecules in various tumor tissues and normal tissues using the TCGA database." (PMID 38287266, 2024). "Il1α, Ccl2, Cxcl5, and Cxcl10 were significantly downregulated in Ifi35ko 4T1 tumor cells." (PMID 38216673, 2024). "CXCL5, a chemokine, promoted tumor cell proliferation and metastasis through multiple pathways." (PMID 38638428, 2024). "CXCL5 recruits neutrophils into tumor tissue and promotes tumor cell proliferation and metastasis." (PMID 39235457, 2024). "In parallel, it also facilitates chemotaxis of myeloid‐derived suppressor cells (MDSCs) by tumor‐derived CXCL5 in an AMP‐dependent manner, which may potentially contribute to enhanced immunosuppression." (PMID 37867243, 2023). "Hence, CXCL5 secreted by tumor cells increases TANs infiltration, leading to a positive feedback loop." (PMID 38138981, 2023).